RSAD2 (radical S-adenosyl methionine domain containing 2)
Diseases named in the same sentence as RSAD2 in open-access papers (continued):
Sharing a sentence is not in itself a finding about the gene and the disease.
infection (continued). "Similarly, the expression of RSAD2 (Viperin), an antiviral protein that inhibits viral budding and release, was decreased in Vero cells following infection, whereas milk supplementation restored its expression." (PMID 41157297, 2025). "Additionally, ROC and logistic regression analyses revealed that the combined expression of IFIT1 and RSAD2 effectively distinguishes HPV16 and GV infections, underscoring their diagnostic value." (PMID 40510586, 2025). "Infection with different viruses leads to differences in RSAD2 expression levels." (PMID 39334325, 2024). "Moreover, we analysed the changes in RSAD2 protein and mRNA levels in PK-15 cells and found that SVA infection triggered a decrease in RSAD2 protein levels and induced peak RSAD2 mRNA levels at 12 hpi, followed by a decrease." (PMID 39334325, 2024). "Moreover, transcription of the IRF3-dependent genes Ifit3 and Rsad2 was significantly increased upon infection with MCMV M35stop compared to MCMV REV." (PMID 37289084, 2023). "Furthermore, all identified infection-associated ISG genes (MX1, MX2, OAS1Y/Z, OAS2, ISG15, IFI6, IFI44 and RSAD2) showed lower expression values in Holstein infected cells relative to Sahiwal." (PMID 35061738, 2022). "Expression of ISG15 and RSAD2 displayed a sharp time-dependent increase following ORFV infection." (PMID 31963559, 2020). "Results revealed that, during the first 3 h of infection, at least 96 transcripts associated with immune responses (e.g. ISGs, MX1, RSAD2, A3C, ID1, CRIP1, TRIM25 and MDA5), apoptosis (ID1, ATF3, TNFα, and RNF7), and pro-inflammatory responses (e.g. PD-L1, CCL8, CXCL10 and CCL17) were downregulated." (PMID 28388950, 2017). "The selected targets included genes that were differentially expressed in both gt1‐ and gt3‐infected samples versus controls (CXCL9, IFIT1, ISG15 and RSAD2), as well as genes that were differentially regulated only in gt1 infection (USP18) or gt3 infection (IDO1)." (PMID 25800823, 2015). "Furthermore, CPIV3 infection significantly inhibited the transcription of the ISGs (RSAD2 and STAT1) in poly(I:C)-stimulated cells, which both implied that CPIV3 infections have evolved efficient strategies to antagonize the induction of endogenous type I IFNs." (PMID 35632770, 2022). "RSAD2 is upregulated in chicken kidney samples following avian infectious bronchitis virus exposure, suggesting that RSAD2 might be induced during early infection." (PMID 31412766, 2019). "Neutrophil RNA markers of viral infection, IFI27 and RSAD2, were identified from COVID19 cases and the literature to provide a more complete picture of the infection profile." (PMID 41385588, 2025). "Blood samples were drawn in RNA preservative (Tempus) and whole blood RNA was analyzed by droplet digital PCR (ddPCR) for RNA transcripts related to neutrophil response to infection by bacterial (DEFA1; ALPL, IL8RB/CXCR2), and viral (IFI27, RSAD2) pathogens." (PMID 41385588, 2025). "Upon infection, this configuration drives robust activation of type I interferon signaling via IRF3, upregulation of key interferon-stimulated genes (ISGs; Mx1, Rsad2), and concurrent suppression of virus-required metabolic pathways (P450, ACSF)." (PMID 41574307, 2025). "Transcriptome analysis of this study showed that untreated infection induces a strong ISG signature, including IFIT1–IFIT3, OASL, RSAD2, and MX1, consistent with canonical antiviral programs." (PMID 41480150, 2025). "The results showed that RSAD2 and IFIT1 effectively distinguished HPV16 infection from healthy controls and GV infection from untreated controls (AUC > 0.7), indicating significant diagnostic potential." (PMID 40510586, 2025). "We identified 6 genes found to be common in all three levels of infection whose expression level increases withthe increase in the level of infection (OASL, IFI27, IFIT1, IFIT3, RSAD2, IFI44L)." (PMID 40255307, 2025).
infection (continued). "According to the previous study, the identified 6 genes were found to be common in all three levels of infection whose expressionlevel increases with the increase in the level of infection (OASL, IFI27, IFIT1, IFIT3, RSAD2 and IFI44L)." (PMID 40322700, 2025). "For example, EV71 or CSFV infection significantly increases RSAD2 mRNA and protein levels, which differs from the effects of SVA infection." (PMID 39334325, 2024). "Compared with mock infection, SVA infection reduced the protein expression and increased the transcript level of RSAD2, which peaked at 12 h post-infection (hpi)." (PMID 39334325, 2024). "In our study, the mRNA level of RSAD2 significantly increased, whereas its protein expression level decreased during SVA infection." (PMID 39334325, 2024). "Despite BA.4 and BA.5 replicating similarly to BA.2 in HAEs, we consistently observed reduced innate activation, measured by ISG induction, after BA.4 and BA.5 infection (IFNB, CXCL10, IFIT1, IFIT2, DDX58 and RSAD2)." (PMID 38228858, 2024). "Considering the strain-specific proteins without a dependency on SLAMF1, Y strain infections displayed one common upregulated protein (RSAD2), and VFRA strain infections had one common downregulated protein (PLD3)." (PMID 39000601, 2024). "Progressing to 16 h post-infection, the expression of genes related to lipid raft formation, such as BST2 appeared, was upregulated, and the expression of the antiviral gene RSAD2 was upregulated." (PMID 39872814, 2024). "RSAD2 also inhibits several steps of viral translation, as demonstrated during HEK 293 cell infection with WNV or DENV." (PMID 35891533, 2022). "Infections with both EHI0418Y05 and EHI0169Y07 elicited a significant rise in IFN-β transcript (p ≤ 0.001), but IFN-stimulated genes, IFITM1, RSAD2, and ISG15, were expressed at higher levels following infection with EHI0418Y05 than with EHI0169Y07." (PMID 35208767, 2022). "In HCV-infected liver biopsies, ARHGEF3 was modestly upregulated 1.5–2-fold during HCV gt1 and gt3 infection; by comparison, IFI27 and RSAD2/VIPERIN were induced >10–100 fold during HCV infection." (PMID 36016278, 2022). "The results showed that infection of these ZIKV strains also induced mRNA and protein expression of TRIM22, which is consistent with other ISGs, such as MX1, IDO1 and RSAD2." (PMID 36042495, 2022). "The stimulatory effect of IFNT on RSAD2, IFIT3 and MX1 was inhibited to a greater extent by HO infection and only HO inhibited GBP4 and HERC5 expression." (PMID 33898551, 2021). "In the presence of HO infection, the stimulatory effect of IFNT on expression of GBP4, ISG15, HERC5, RSAD2, IFIH1, IFIT3, and MX1 was significantly reduced (IFNT vs. IFNT+HO, P < 0.05–0.01)." (PMID 33898551, 2021). "Infection with either HO or KY alone had similar inhibitory effects on most ISGs (ISG15, GBP4, HERC5, RSAD2, DDX58, and IFIT3), although a slightly greater inhibitory effect of HO was observed on IFI27 and MX1." (PMID 33898551, 2021). "After prolonged HEV gt3 infection for more than 3 months, significantly lower expression levels of STAT1, RSAD2 and MX1 compared to uninfected controls were observed, suggesting possible viral interference with the host’s cell innate immune signaling." (PMID 28811492, 2017). "MR-1947 infection exhibited enhanced kinetics and magnitude of antiviral effector gene transcription, with IFIT family members and RSAD2 being induced as early as 12hpi." (PMID 28152048, 2017). "In contrast, 43 genes associated with innate immune cells were down-regulated following YFV-DakH1279 infection and only three genes were upregulated (KLRC1, CPA3 and RSAD2)." (PMID 25412185, 2014). "Increased RNA expression levels of the ISGs Mx2, Rsad2, and USP-18 mRNA were found in both WT and IRF-1−/− 2 days post infection, followed by a decline." (PMID 24675692, 2014).
infection (continued). "Importantly, infection with LSDVΔ122 partially but significantly enhanced IFN-β-induced transcription of antiviral ISGs, including ISG56, MX2, and RSAD2, compared to wild-type LSDV." (PMID 41525414, 2026). "Following testosterone substitution of female mice, a noticeable trend towards decreased RSAD2-expressing neutrophils from blood, but not the liver, was observed after infection." (PMID 38179044, 2023). "Notably, multiple antiviral proteins were also dramatically decreased in PAMs during the PRRSV-ADE infection, including ISG15, ISG20, IFIT1 (ISG56), IFIT2 (ISG54), IFIT3 (ISG60), IFIT5 (ISG58), OAS1, Mx1, RSAD2, TRIM22, TRIM25 and TRIM34, except for TRIM52." (PMID 36680075, 2022). "Considering direct connection of RSAD2 with Type I interferons, we can see the opposite picture in group 6, where treatment was a combination of FPI and ibuprofen and started early (on day 3 after the infection)." (PMID 33600498, 2021). "At the transcriptome level, the high expression levels of viral sensors MDA5 (IFIH1), R1G-1 (DDX58), and ISGS (ISG15, Mx1, Mx2, RSAD2, IFIT3, and IFIT5) and transcription factors like IRF-7 and STAT-1 that induce ISG expression were found in lymphocytes during virulent PPRV infection." (PMID 34631844, 2021). "However, in response to infection, male mice exhibited higher expression levels of CXCL2 (KO, 1A3, and 6A2), SAMHD1 (1A0, 1A3), RSAD2, STAT1, and STAT3 (1A0), MYD88 and PSMB8 (1A3), BCL3, BCL10, CCRL2, IFITM2, RTP4, and ZFP36L1 (6A2), compared to females." (PMID 32670284, 2020). "We observed increased IFNB1, IL29/IFNL1, IL28A/IFNL2, IFNL3, RSAD2, and CXCL10 post infection." (PMID 33409274, 2020). "This was further confirmed by RNA fluorescence in-situ hybridization (FISH) targeting RSAD2, showing that RSAD2 mRNA is mainly nuclear following infection with MP12, but not with MP12-ΔNSs." (PMID 29085037, 2017). "In this regard, we found that interferon-inducible antiviral proteins, RSAD2, OAS1, were also upregulated in the period of late infection, suggesting that many of the proteins identified in this study are associated with inflammation, IFN activation, and the innate immune response." (PMID 25333634, 2014). "Although TKO mDC failed to induce Ifnb expression after WNV-NY infection, they retained the ability to respond to its signaling, inducing WT levels of Ifnb, Oas1a, Rsad2, and Cxcl10 at 24 hours after IFN-β treatment." (PMID 23300459, 2013). "Interestingly, even 72 h post-infection in vitro, no large changes were detected compared to the 24 h time point for Rsad2, as measured by qPCR." (PMID 39205301, 2024). "Therefore, we investigated expression of IL-15 and ISGs, such as APOBEC3G, ISG15, ISG20, MX1, MX2, and RSAD2, after infection with R5-tropic, non-opsonized (HIV) and complement-opsonized (HIV-C) HIV-1 strains (BaL and YU-2)." (PMID 34634939, 2021). "However, HBVΔX infection did not induce the expression of two prototypic ISGs, RSAD2 (Viperin) and IFIT1 (ISG56), at any time point post-infection when cccDNA was transcriptionally silent (none or siCtrl)." (PMID 28095508, 2017). "Therefore, we hypothesized that IFN might be induced during early infection, as indicated by the subsequent enhanced production of ISGs because increased expression of a variety of ISGs, such as OSAL, MX1, IFIT5, ISG12-2, RSAD2, IFI35, protein kinase R (PKR), and IFI27L2, was found in this study." (PMID 24168272, 2013). "Expression levels of RSAD2, ISG15, IFI44L, and IFI27 were strongly correlated to serum sCD163 levels early after infection, but not to T-cell activation, suggesting that ISG expression may be linked to monocyte activation." (PMID 39104769, 2024).
tumor (25 papers, 2012 to 2025). "RSAD2 served as an independent risk factor capable of predicting tumor stage, grade, and lymph node metastases in BC." (PMID 40707929, 2025). "RSAD2, an interferon-inducible gene and an emerging biomarker in cancer, was found to drive tumor progression in preclinical studies." (PMID 41439936, 2025). "From the current study, RSAD2 gene expression was found to be heightened in HCC patients’ tumor tissues and/or peripheral blood leucocytes." (PMID 41439936, 2025). "Genes implicated in the modulation of tumor microenvironment and immunomodulation include CLIC5, RSAD2 and OASL." (PMID 40312750, 2025). "RSAD2 knockdown in cancer cell lines was shown to suppress tumor progression and reverse metabolic reprogramming, implicating it as a driver of tumor proliferation." (PMID 41439936, 2025). "Previous research has suggested that RSAD2 influences tumor immune status via interferon-stimulated pathways." (PMID 40510586, 2025). "qPCR analysis of the dissociated tumour cells revealed that the delivery of immRNA‐loaded RBCEVs led to the up‐regulation of Ddx58, Mda5, Mavs, Irf3, Irf7, Ifnb, Rsad2, and Isg56 in the tumours." (PMID 35430766, 2022). "ROC curve analysis showed that CXCL8, DDX60, IFI44l, RSAD2, and RTP44 had better diagnostic efficiency for normal and tumor tissues, and the combined diagnosis was more effective." (PMID 34384424, 2021). "In the first part of the study, we evaluated whether RSAD2 was differentially expressed in HCC tumor samples compared to normal tissues using genomic repositories." (PMID 41439936, 2025). "Although the initial CCM screen evaluated associations with a gene signature of immune activity, including TLS formation, the emerging CCMs covered genes that are expressed by tumor cells (e.g., RSAD2, CMPK2) and stromal fibroblasts (e.g., SUCNR1) as well as immune cells (e.g., POU2F2)." (PMID 40723216, 2025). "Finally, Cluster 8 was equally conserved across healthy and tumor-associated neutrophils and was enriched for IFN markers: Isg15, Rsad2, Ifit3, Ifit1, and Slfn4, a phenomenon previously reported in several scRNA-seq studies of neutrophils." (PMID 38358352, 2024). "However, the expressions of IGKC, IGLC1, ITGB2, CTSS, HLA‐DPB1, and RSAD2 were elevated in tumor tissue and they served as protective factors." (PMID 37543714, 2023). "Additionally, low and medium protein expressions of RSAD2 were seen in normal and tumor tissues, respectively." (PMID 34439992, 2021). "However, in RSAD2 knockout mice with lung metastasis, MDCs lose their anti-tumor effect, which also reflects that antigen-presenting cells are crucial for inducing cancer immunity." (PMID 34384424, 2021). "Finally, to examine antitumor responses in vivo, B16F10 tumor-bearing mice were immunized with mDCs or Rsad2 knockdown mDCs and survival evaluated." (PMID 30068989, 2018). "Tumor-bearing mice then received subcutaneously two injections of mDCs or Rsad2 knockdown DCs." (PMID 30068989, 2018). "The Human Protein Atlas database showed that the protein expressions of DDX60, IFI44L, RSAD2, and RTP44 in tumor tissues were higher than those in normal tissues." (PMID 34384424, 2021). "RSAD2, an interferon-inducible gene, is upregulated by the PI3K/AKT/mTOR pathway and serves as a key factor for metabolic reprogramming to promote stem-like properties of cancer stem cells and tumor proliferation." (PMID 41439936, 2025). "Direct contributions of CMPK2 and RSAD2 to anti-tumor immune response induction, as opposed to serving as indirect biomarkers of interferon signaling, should be clarified." (PMID 40723216, 2025). "We then used the Tumor IMmune Estimation Resource (TIMER) database, which allows the analysis of immune infiltrates from RNA expression data across different cancer types, to test the influence of RSAD2 and IFIH1 on immune cell infiltration." (PMID 32978520, 2020).
tumor (continued). "Another integrated mRNA–lncRNA signature was developed based on the mRNA species for FCGR1A, RSAD2, CHRDL1, and the lncRNA species for HIF1A-AS2 and AK124454, which may be applied to predict tumor recurrence and the benefit of taxane chemotherapy in TNBC." (PMID 33194705, 2020). "Likewise, interferon response genes (including TLR3, MX1, RSAD2, IFI44, IFI27, IFIT1, and IFIT3), and chemokine genes (including CCL7, CXCL10, CXCR1, and CCL25) were significantly increased in PM-treated MM tumor tissues, whereas panobinostat showed minimal effects at equivalent doses." (PMID 40562746, 2025). "Second, tumor subsets enriched for microenvironment features, including hypoxia markers (e.g., Slc2a1, Pdk1, Car9), extracellular matrix (ECM) genes (e.g., Matn2, Fn1, Dcn, Col6a1), vasculature (e.g., Cdh5, Pecam1, Vwf), and interferon response genes (e.g., Rsad2, Ifit3, Gbp3, Cxcl10, Cd274)." (PMID 40171265, 2025). "The interferon response gene RSAD2, upregulated mechanistically by the JAK/STAT interferon response and PI3K/AKT/mTOR pathways, is a key factor for metabolic reprogramming to enhance lipogenesis and glycolysis, thereby promoting stem-like properties of cancer stem cells and tumor proliferation." (PMID 41439936, 2025). "Furthermore, the ROC curve analysis showed that hub gene (CXCL8, DDX60, IFI44L, RSAD2, and RTP4) could distinguish OC from normal tissues, and the diagnosis effect of tumor tissue was better, and the combined diagnosis of five genes was the best." (PMID 34384424, 2021).
cancer (15 papers, 2010 to 2026). A tumor composed of atypical neoplastic, often pleomorphic cells that invade other tissues. "Both ID1 and RSAD2 have been implicated in regulating glycolytic pathways in cancer." (PMID 39334961, 2024). "Studies evaluating RSAD2 in other cancers commonly reported its prognostic value with mixed findings." (PMID 41439936, 2025). "The association between RSAD2 and extra-metastasis is compatible with the current mechanistic knowledge of RSAD2 in cancers." (PMID 41439936, 2025). "Further research is needed to examine the clinical significance of RSAD2 gene expression in other cancer types." (PMID 41439936, 2025). "Prognostic studies of RSAD2 in cancer were mainly genomic analyses using public databases." (PMID 41439936, 2025). "Importantly, specific representatives of the residual signature genes (ISG15, IFI27, IFI6, RSAD2) appear to aid cancer cells in evading immunosurveillance and inflammatory cells by inhibiting apoptotic processes." (PMID 40312750, 2025). "Indeed, the expression of CCL8, IFIT1, IFIT3, IFI27, MX1, and RSAD2 has previously been considered favorably prognostic in several types of cancer." (PMID 36180872, 2022). "Dedicated prognostic studies of RSAD2 with relevant and comprehensive clinical data from patients with cancer are lacking." (PMID 41439936, 2025). "Transcriptional analyses of IL-6, RSAD2, IFIT1 and IFNB1 following treatment with the CPT analogue topotecan (Top) suggested that 15 and 21 out of 42 human cancer cell lines expressing STING showed increased IL-6 expression >2 fold after 6 and 24 h Top treatment, respectively." (PMID 35087822, 2021). "For examples, RSAD2, involved in antiviral defense, has not been reported as being related to cancer, as well as SGPP2, known to be involved in pro-inflammatory signaling, and CST4." (PMID 21060876, 2010). "This concurrent induction of Il-6, Rsad2 and Ifit1 by CPT in TC-1 cells prompted us to broadly assess whether such convergent induction of the NF-κB and IRF3 branches was a frequent response to DNA damage in cancer cells." (PMID 35087822, 2021).
bacterial infections (3 papers, 2022 to 2024). "RSAD2 is an IFN-stimulated protein that restricts various families of viruses, while PLD3 digests ssRNA and ssDNA in lysosomes/endosomes in viral and bacterial infections." (PMID 39000601, 2024). "Moreover, among the genes upregulated in pigs, genes involved in viral or bacterial infections, such as IFI44L, IL33, and RSAD2, were ranked at the top of the list." (PMID 38998110, 2024).